INS (insulin)
Diseases named in the same sentence as INS in open-access papers (continued):
Sharing a sentence is not in itself a finding about the gene and the disease.
Insulin resistance (continued). "However, if the hepatic insulin signaling cascade becomes impaired, as happens in the case of insulin resistance, pathologies in hepatic metabolism arise and the liver itself becomes a critical contributor to hyperglycemia, inflammation, and de novo lipogenesis." (PMID 32545342, 2020). "Consistent with the observed insulin resistance the sucrose group showed increased circulating levels of both insulin (5.8 ± 0.1 to 40.3 ± 5.6 ng/mL, *** p < 0.001) and c-peptide (3457 ± 788.2 to 6943 ± 922.6 pmol/L, * p < 0.05), pointing a failure in insulin secretion and action." (PMID 32942712, 2020). "Consequently, improvement of leptin and insulin resistance by hesperidin treatment alone and/or in combination with orlistat might be in part by improvement in serum and tissue levels of leptin and insulin respectively as found in results." (PMID 31929574, 2020). "Carrageenan, a thickening and stabilizing agent, used in >5,500 products in France and in the top-20 used additives, might increase insulin resistance and inhibit insulin signalling in mouse liver and human HepG2 cells, which might, in turn, induce weight gain." (PMID 32853224, 2020). "The obese HFD+B29 mice also exhibited statistically significant elevations in blood glucose and insulin levels (both fasted and 30 min postchallenge) and a marked decrease in glucose tolerance relative to all other groups, consistent with features of insulin resistance." (PMID 32019793, 2020). "Therefore, in the presence of insulin-resistance, the insulin-sensitizing properties of inositols could play a relevant role on sperm function." (PMID 32392776, 2020). "Because insulin resistance is defined as an inability of peripheral tissues, such as the skeletal muscle, liver, and adipose tissue, to increase glucose uptake in response to insulin, we further investigated which of these tissues had become insulin resistant in 25-week-old α7−/− mice." (PMID 32708537, 2020). "However, if insulin resistance develops and the beta-cell compensation of the pancreas is inadequate in secreting sufficient insulin to maintain normal glycemia in the mother, gestational diabetes mellitus may occur." (PMID 33081304, 2020). "Some studies have focused on the association between bilirubin and insulin resistance; however, few studies or analyses have used HEC, the “gold standard” to evaluate GDR (M value) when researched the relationship between serum bilirubin and insulin sensitivity." (PMID 32802055, 2020). "Potent synthetic PPARγ ligands such as MRL24 or rosiglitazone (both widely used as insulin-sensitizing anti-diabetic drugs) were proposed to shield Ser273 residue from phosphorylation by Cdk5, thereby restoring expression of adiponectin and overcoming insulin resistance." (PMID 31910742, 2020). "Through a comparison of the causal estimates of BMI and WHRadjBMI on glycemic traits (fasting glucose, fasting insulin, HOMA-IR, and HbA1c), this study further emphasizes that overall and abdominal obesity might increase the T2DM risk mainly via elevation of insulin resistance." (PMID 32714368, 2020). "Since insulin promotes net hepatic lipogenesis in standard conditions, insulin-resistant patients should be characterized by decreased lipogenesis, and such a phenotype was described in mice with total genetic insulin resistance (ablation of the hepatic insulin receptor)." (PMID 32545342, 2020). "In non-obesity insulin resistance state, there might be a selective loss of insulin function possibly through PKC axis instead of AKT (PKB) axis." (PMID 32670384, 2020). "Thus, to test if the body fat percentage may be a factor contributing to insulin resistance in the OSA group, we tested its association with different biochemical variables and insulin sensitivity indices derived from them." (PMID 32562183, 2020).
Insulin resistance (continued). "This study revealed that G. lucidum could effectively prevent obesity and insulin resistance by attenuating adipocyte hypertrophy and dyslipidemia and improving homeostasis by recovering insulin sensitivity and adipokine function in HFD-induced obese C57BL/6 mice." (PMID 33142995, 2020). "In addition, absolute body fat content is inversely correlated with antioxidative status and α-TOH concentration, which itself inversely correlates with fasting plasma insulin concentration and the Homeostatic Model Assessment of Insulin Resistance (HOMA-IR) index." (PMID 33003543, 2020). "In addition, the dampening of insulin-induced S22 phosphorylation observed in BAT from HFD-fed mice could indicate a potential role in the pathogenesis of insulin resistance." (PMID 32249683, 2020). "Regarding adiponectin and leptin, our finding showed that a diet with low AGEs content could significantly increase adiponectin and decrease leptin levels, two important markers of insulin resistance, suggesting that diet derived AGEs also have effects on insulin sensitive tissues." (PMID 33335235, 2020). "Similarly, we failed to reject the null hypothesis of no change from pre‐ to postintervention for fasted plasma glucose, TAG, FGF21, GLP‐1, serum insulin concentrations, homeostatic model assessment of insulin resistance, or serum osmolality (all P ≥ 0.136)." (PMID 32108442, 2020). "Thus, SFRP2 was related to insulin sensitivity and insulin resistance." (PMID 32517740, 2020). "Hence, decreased levels of MME, as we observed in the overweight cohort, may play a role in the deregulation of insulin response and insulin resistance." (PMID 32012940, 2020). "Also, the peripheral insulin resistance is known to raise serum insulin levels which inhibit insulin transporters in the blood-brain barrier and thereby might reduce CNS insulin levels." (PMID 33024433, 2020). "However, in individuals or rodents where insulin sensitivity is decreased, and insulin resistance is increased such as the prediabetic animal model in this study, the compensatory mechanisms counteract the prolonged glucocorticoid-induced insulin resistance resulting in hyperglycaemia." (PMID 33308255, 2020). "Additionally, a bidirectional influence between leptin and insulin exists, with hyperinsulinemia enhancing leptin production and increased free leptin levels increasing insulin resistance, with “leptin resistance” and IR usually coexisting in obesity, even at young ages." (PMID 33137934, 2020). "Therefore, the activation of inflammatory pathways other than the vagus nerve interferes with insulin and leptin signaling in the brain and also in peripheral tissues, contributing to insulin resistance in obesity and metabolic disorders, such as type 2 diabetes." (PMID 33353562, 2020). "However, clinically insulin resistance is measured by the inability of insulin to regulate glucose." (PMID 33365205, 2020). "As central insulin and dopamine action are interlinked and have impacts on mood, reward, and food intake, the dopaminergic system could become compromised under brain insulin resistance." (PMID 32971941, 2020). "However, there are several genetic syndromes of severe insulin resistance that have illuminated our understanding of the basic biology of insulin signaling and resistance, for example, the autosomal recessive insulin receptor (INSR) defects seen in Donohue syndrome and Rabson-Mendenhall syndromes." (PMID 33210059, 2020). "Thus, higher AUCCP may represent higher endogenous insulin secretion and may be a compensatory of insulin resistance due to higher SUA, namely, higher AUCCP is a sign of insulin resistance, which plays important role in the progress of NAFLD." (PMID 33329401, 2020).
Insulin resistance (continued). "Furthermore lots of experiments and clinical trials have shown that resveratrol had beneficial effects on T2DM by improving glucose homeostasis, decreasing insulin resistance, protecting pancreatic beta-cells, improving insulin secretion and ameliorating metabolic disorders." (PMID 33292335, 2020). "Moreover, C-peptide level is a more sensitive indicator of insulin resistance than insulin level." (PMID 33180852, 2020). "In line with that, our results highlighted significant correlations between handgrip strength and HbA1c, plasma glucose, plasma insulin and HOMAIR, indicating that strength development may have played a role in improving insulin resistance and cardiometabolic risk factor." (PMID 33467267, 2020). "Furthermore, overexpression of Hepassocin (HPS), a liver-derived protein, promotes lipid accumulation through an ERK1/2-mediated pathway, and recombinant HPS administration aggravates insulin signaling to induce insulin resistance through an ERK1/2-mediated signaling in hepatocytes." (PMID 32872540, 2020). "Cardiac biopsies and the investigation of insulin signaling molecules, such as insulin receptor substrate 1 (IRS1), IRS1-associated PI3K (IRS1-PI3K), and GLUT4, may be alternative and direct diagnostic methods to evaluate myocardial insulin resistance." (PMID 31330848, 2019). "Therefore, we next asked whether altering PLIN5 expression in islets would influence systemic insulin resistance detected by ITT as a few AAV were also detected in insulin targeted tissues such as liver, muscle and visceral fat." (PMID 31384284, 2019). "A balance between free radical generation and scavenging is crucial at a cellular level, and any imbalances may result in an oxidative stress environment that alters insulin sensitivity by either increasing insulin resistance or impairing glucose tolerance via several cell signalling pathways." (PMID 31718066, 2019). "Although clinical studies have shown the association between phospholipids and insulin sensitivity, it is still not clear whether changes in phospholipids are the cause or consequence of insulin resistance." (PMID 30402908, 2019). "As adiposity is an important determinant of insulin resistance, we next assessed whether the fat body of the cardiac-specific Sna-knockdown flies, which stores more fat than the control fat body, could have altered insulin sensitivity." (PMID 31725726, 2019). "It was hypothesized that the GH-induced insulin antagonistic effect is strongly related to the lipolytic effects of GH, as free fatty acids released from fat stores inhibit glucose disposal, resulting in insulin resistance." (PMID 31417493, 2019). "The persistent insulin resistance in gestational diabetes may be related to inflammatory factors, mediated by action of placental hormones and other cytokines, affecting the postreceptor insulin signaling cascade." (PMID 31828161, 2019). "Putting together these data leads to the hypothesis that a single molecular impairment in the pathway of insulin signaling, including an incomplete interaction between PIK3CA(OMIM association number, 171834) and IRS1, may lead to insulin resistance, as well as insulin secretion defect." (PMID 30884193, 2019). "Notably, insulin resistance per se may lower energy demand, as insulin will be less able to stimulate ATP-consuming anabolic processes." (PMID 31195596, 2019). "The present study showed that the HFFD diet caused obesity, insulin resistance, hyperinsulinemia, and dyslipidemia associated with MetS through impaired parameters such as increased body weight, cholesterol levels (TC, TG, LDL, VLDL, and non HDL), fasting glucose concentration, and insulin level." (PMID 31171927, 2019). "We observed that short- and medium-chain acylcarnitine levels after glucose load were reduced equally in control and HFD-induced insulin resistant animals, and no consistent association between changes in plasma levels and the degree of insulin resistance was observed." (PMID 31920980, 2019).
Insulin resistance (continued). "Collectively, these suggest that uncorrected insulin resistance may contribute to antidepressant treatment resistance in some depressed patients and that treatment response in this group may be enhanced by improving insulin sensitivity." (PMID 30803432, 2019). "Furthermore, hyperuricemia itself may directly contribute to insulin resistance via inhibition of insulin signaling or as a result of decreased endothelial nitric oxide bioavailability." (PMID 31212821, 2019). "Further, central insulin resistance could potentiate the development of obesity and peripheral insulin resistance via the disruption of insulin signaling in the homeostatic and hedonic circuitry, alteration of hepatic lipogenesis and white adipose tissue metabolism." (PMID 31754139, 2019). "Insulin resistance is a low-grade chronic inflammation state and inflammation in the muscle microvasculature blunts insulin-mediated microvascular recruitment and reduces trans-endothelial insulin transport, thus reducing insulin delivery to and action in muscle." (PMID 30699907, 2019). "However, co-morbidities could also be consequences of insulin and insulin resistance so their consideration in the model would give the direct effects of insulin rather than the total effect sought, i.e., might create bias." (PMID 31508506, 2019). "A mechanism potentially explaining these associations may be that 2-AAA is elevated in response to high glucose levels, leading to increased insulin secretion and promoting mechanisms involved in maintaining glucose homeostasis in early stages of insulin resistance." (PMID 31722714, 2019). "Additionally, depression and age had indirect unfavorable effects on some insulin resistance indices such as homeostasis model assessment of insulin resistance (B = 0.07; p<0.05, for age) and quantitative insulin sensitivity check index (p<0.05, for age and depression) via HEI." (PMID 31260504, 2019). "Inflammatory cytokines secreted by adipose tissue, such as interleukin 6 (IL-6) and tumor necrosis factor alpha (TNF-α), may exert an endocrine effect to promote insulin resistance by interfering with the insulin signalling pathway, leading to the clinical manifestation of T2DM." (PMID 31485456, 2019). "Hepatic insulin resistance results in the elevation of hepatic glucose production and triglyceride (TG) accumulation (by impairing insulin-mediated inhibition of gluconeogenesis and regulating insulin-mediated TG metabolism, respectively), which contributes to hyperglycaemia and dyslipidaemia." (PMID 30720717, 2019). "The 3T3-L1 adipocytes develop insulin resistance in response to insulin, TNF or saturated fatty acids, and transcriptional response to TNF begins within the first 1 h of the treatment, and changes in protein phosphorylation associated with insulin resistance can be detected as early as 6 h." (PMID 31635166, 2019). "In addition, we could detect significantly increased fasting circulating plasma insulin levels and increased insulin resistance by using insulin tolerance test." (PMID 31165747, 2019). "The best correlate of follow-up insulin resistance (M/I) was baseline M/I, followed by inverse correlations with central adiposity, measured by visceral fat volume and waist circumference, fat-free mass, BMI, diastolic blood pressure, fasting serum insulin and liver fat." (PMID 31071971, 2019). "However, contrary to conventional wisdom’s prediction that elevating mitochondrial fatty acid oxidation would attenuate the progression toward insulin resistance in skeletal muscle, ACSL-5 was also associated with increased free radical production (i.e., O2− ) and reduced insulin signaling." (PMID 30935113, 2019). "Third, the serum levels of insulin were not routinely measured in NF patients, and we could not evaluate the association between the glycemic gap and insulin resistance." (PMID 31581199, 2019).
Insulin resistance (continued). "The vast majority of the works related to the problem of obesity and insulin resistance focused on the metabolism of sphingolipids in skeletal muscles, which constitute 40% of the human body and are responsible for 70–80% of whole body insulin-stimulated glucose uptake." (PMID 31496996, 2019). "There is also growing evidence that anti-TNF-α biological drugs used to treat rheumatoid arthritis (RA) can improve insulin sensitivity and reduce insulin resistance in RA patients, raising the possibility that targeting proinflammatory pathways may also have therapeutic benefits in T2DM patients." (PMID 30719343, 2019). "Moreover, serum irisin levels were inversely correlated with adverse metabolic parameters including WC, WHR, creatinine, HOMA-IR and fasting insulin, suggesting that irisin may play a role in obesity related insulin resistance." (PMID 31881940, 2019). "In addition to the possible genetic pathways associated with hyperandrogenism, genetic predispositions for obesity, insulin resistance and T2DM may help explain disruptions of insulin pathways that can result in PCOS." (PMID 31367382, 2019). "Interestingly, recent data show a positive correlation of ANGPTL3 with plasma glucose, insulin, and homeostatic model assessment of insulin resistance (HOMA-IR) in insulin-resistant states, implying that ANGPTL3 may also participate in glucose homeostasis." (PMID 30944669, 2019). "Asians, such as the Japanese, also have lower insulin resistance and insulin secretion than Westerners at the same level of visceral adipose tissue, and the mechanisms involved in the development of insulin resistance and metabolic dysfunction might differ between Asian and Western populations." (PMID 31697720, 2019). "TNFα and IL6, which are both positively associated with insulin resistance (Hotamisligil, Shargill, & Spiegelman, 1993; Pickup, Mattock, Chusney, & Burt, 1997), were increased in plasma of HFD‐fed Park2 KO mice, inconsistent with the observed phenotype with regards to insulin sensitivity." (PMID 31724300, 2019). "Importantly, longitudinal changes of insulin sensitivity are strongly related specifically to fat mass accrual over time, highlighting the mechanistic role of adipose tissue excess in the development of insulin resistance." (PMID 31474943, 2019). "However, the present work is the first to examine and verify the defects in insulin signaling in the hippocampi of AlCl3-treated rats to demonstrate that insulin resistance and wrecked insulin signaling have started when AlCl3 insult promoted IRS1 serine phosphorylation." (PMID 31137621, 2019). "However, why some patients' glucose tolerance status fails to improve postoperatively and which factors are involved, such as GH, IGF-1, acromegaly remission status, pancreatic β-cell function, insulin sensitivity and insulin resistance (IR), remains unclear." (PMID 31736874, 2019). "Furthermore, plasma insulin concentration and insulin resistance were significantly reduced in whole egg group only, Which suggests that egg diet might be effective in managing metabolic syndrome." (PMID 30744071, 2019). "Thus, we hypothesize that aspalathin, in addition to improving insulin signaling, is likely to target the mitochondrion to increase energy expenditure and reverse insulin resistance." (PMID 31048842, 2019). "However, we acknowledge that insulin resistance markers may reflect a composite state of insulin sensitivity levels of multiple tissues." (PMID 31779625, 2019). "Moreover, other natural products, such as silibinin, the major active constituent of silymarin, show potential to ameliorate palmitate-induced insulin resistance in C2C12 myotubes through increased insulin-stimulated glucose uptake and via modulation of the IRS1/PI3K/AKT pathway." (PMID 30717198, 2019).